GDF3 (growth differentiation factor 3)
Diseases named in the same sentence as GDF3 in open-access papers (continued):
Sharing a sentence is not in itself a finding about the gene and the disease.
Sepsis (5 papers, 2020 to 2024). Sepsis is defined as life-threatening organ dysfunction caused by a dysregulated host response to infection. "Taken together, this study uncovers that GDF3, as a novel sepsis-associated factor, may have a dual role in the pathophysiology of sepsis." (PMID 31947892, 2020). "Consequently, in ALI and other organ injuries caused by sepsis, GDF3 may be a promising therapeutic target." (PMID 38543054, 2024). "However, constitutive high levels of GDF3 in human sepsis patients are associated with lethality, suggesting that GDF3 may promote macrophage polarization toward M2 phenotype which could lead to immunosuppression." (PMID 31947892, 2020). "However, in human sepsis patients, constitutive high levels of GDF3 might be associated with lethality because GDF3 could promote macrophage polarization toward M2 phenotype which leads to immunosuppression." (PMID 31947892, 2020). "In a mouse sepsis model, administration of GDF3 has demonstrated improvements in cardiac function, suppression of the inflammatory cytokine IL-1β, and a reduction in mortality." (PMID 38543054, 2024). "Previous investigations conducted by our team have confirmed a significant upregulation of GDF3 expression in the serum of sepsis patients in comparison with healthy controls." (PMID 38543054, 2024). "Accumulating evidence has demonstrated a close relationship between GDF3 expression and the severity and prognosis of sepsis." (PMID 38543054, 2024). "These collective findings unequivocally indicate the protective effects of GDF3 against sepsis-induced ALI." (PMID 38543054, 2024). "Our recent study demonstrated that patients with sepsis exhibited significantly higher levels of serum GDF3 as a compensatory mechanism in response to septic shock, suggesting the potential role of GDF3 in treating sepsis." (PMID 33679812, 2021). "Our study presented here defines a previously unrecognized role of GDF3 in macrophage polarization and endotoxin/sepsis-induced cardiac injury." (PMID 31947892, 2020). "To further clarify the capacity to predict mortality by serum GDF3 levels in sepsis patients, we conducted an ROC curve analysis." (PMID 31947892, 2020). "More interestingly, serum levels of GDF3 were greatly elevated in human patients with severe sepsis on admission, which implicates its potential compensatory role in host immune response." (PMID 31947892, 2020). "GDF3 and Sectm1a have been shown to influence cardiac function of septic mice and are potential therapeutic targets of sepsis-induced cardiac dysfunction." (PMID 33986658, 2020). "Acute administration of recombinant GDF3 protein in septic mice protects against endotoxin-induced cardiac dysfunction and sepsis mortality." (PMID 31947892, 2020). "Here, we show that serum GDF3 levels in septic patients are elevated and strongly correlate with severity of sepsis and 28-day mortality." (PMID 31947892, 2020). "On admission, human patients with sepsis exhibited significantly higher serum GDF3 levels compared with healthy donors." (PMID 31947892, 2020). "Second, while endotoxin is a major causative factor for gram-negative bacteria-induced sepsis, it will however be interesting to investigate if GDF3 confers similar protection against true microbe-induced sepsis in the future." (PMID 31947892, 2020). "GDF3 levels showed stronger predictive capacity with AUC value of 0.770 (95% CI, 0.593-0.947, p = 0.033), when compared to other conventional sepsis biomarkers (i.e., lactate (Lac), C-reaction protein (CRP), procalcitonin (PCT) and serum amyloid A (SAA))." (PMID 31947892, 2020). "However, the precise mechanism by which GDF3 protects against ALI induced by sepsis is still unclear." (PMID 38543054, 2024). "Furthermore, our recent studies revealed that serum GDF3 levels in septic patients are elevated and strongly correlate with severity of sepsis and 28-day mortality." (PMID 33679812, 2021).
Sepsis (continued). "Furthermore, receiver operating characteristic (ROC) curves were generated for GDF3 to discriminate sepsis from healthy donors." (PMID 31947892, 2020). "In conclusion, GDF3 may represent a new biomarker candidate for sepsis that could predict mortality and severity." (PMID 31947892, 2020). "Whether GDF3 could serve as a clinical marker of sepsis/septic shock remains to be further validated using a large cohort of sepsis patient samples." (PMID 31947892, 2020). "Furthermore, immunofluorescence staining demonstrated co-localization of the pyroptosis markers Caspase-1 and NLRP3 with the macrophage-specific antibody F4/80, providing further evidence that sepsis-induced lung injury can be prevented by inhibiting macrophage pyrolysis by GDF3." (PMID 38543054, 2024). "However, the role of GDF3 in sepsis-induced ALI remains largely unexplored." (PMID 38543054, 2024). "Therefore, it is hypothesized that GDF3 may be involved in the function of macrophages in sepsis-induced lung injury and that GDF3 can protect against sepsis-induced acute lung injury by inhibiting macrophage pyroptosis." (PMID 38543054, 2024). "Therefore, GDF3 may be of great interest as a potential drug target or mediator to improve clinical outcomes for sepsis patients." (PMID 33679812, 2021). "Therefore, our study indicates that GDF3 may play a previously unrecognized role in controlling bacterial dissemination during sepsis." (PMID 33679812, 2021). "Therefore, these prior findings promoted us to clarify whether GDF3 could regulate macrophage phagocytic function in a clinically relevant sepsis model." (PMID 33679812, 2021). "Given the complexity of sepsis pathophysiology and incomplete knowledge of mediators that drive mortality, the reasons for these discrepancies are unclear but could reflect dual roles of GDF3 in sepsis patho-physiology." (PMID 31947892, 2020). "Nevertheless, the role of GDF3 in macrophage-regulated endotoxemia/sepsis remains unclear." (PMID 31947892, 2020). "Nonetheless, the role of GDF3 in macrophage-regulated endotoxemia/sepsis is unknown." (PMID 31947892, 2020). "It has been reported that GDF3 can enhance macrophage phagocytosis mediated by LXRα and improve survival in CLP-induced sepsis, exerting a protective effect in preventing acute lung injury." (PMID 38543054, 2024). "Thus, GDF3 may serve as a new supplement to immunotherapy treatment of sepsis from a translational viewpoint, and as a potential novel biomarker for the diagnosis of sepsis." (PMID 31947892, 2020). "Interestingly, median GDF3 level of septic shock group was much higher than non-shock sepsis group." (PMID 31947892, 2020).
teratocarcinoma (4 papers, 2006 to 2023). A germ cell tumor characterized by the presence of an embryonal carcinoma component and a teratoma component. "It has been clearly demonstrated that human stella-related (STELLAR), NANOG, and GDF3 genes are expressed in pluripotent cells and mapped to chromosome 12p13, which is a hotspot for teratocarcinoma." (PMID 37205315, 2023). "In human, the chromosome region where NANOG is located also contains DPPA3, POU5F1P3 and another pluripotency factor, GDF3, and collectively is called a ‘hotspot for teratocarcinoma’ owing to the high rate of chromosomal abnormalities." (PMID 36621005, 2023). "The chromosome region with adjacent localization of the genes NANOG, STELLAR, and GDF3 has been considered as a hotspot for teratocarcinoma." (PMID 16670017, 2006).
Klippel-Feil syndrome (3 papers, 2013 to 2023). A congenital, musculoskeletal condition characterized by the fusion of at least two vertebrae of the neck. "Of particular interest were two regions (Chr8, Max LOD = 3.04; Chr12, Max LOD = 2.09) identified within the subset of “CTD-negative” families, both of which harbor growth differentiation factors (GDF6, GDF3) implicated in the development of Klippel-Feil syndrome (KFS)." (PMID 23620759, 2013).
coloboma (2 papers, 2014). An abnormality in which a part of a structure in one or both eyes is missing. "These DNA samples had been previously screened for mutations in two other coloboma-related genes, GDF3 and GDF6." (PMID 25010521, 2014).
microphthalmia (2 papers, 2022). Congenital or developmental anomaly in which the eyeballs are abnormally small. "Although the association between GDF3 and ZIKV pathogenesis is unknown, high serum levels of GDF3 have been linked to skeletal and congenital anomalies such as microphthalmia, iris, and retinal colobomas." (PMID 35632746, 2022).
retinoblastoma (2 papers, 2019 to 2025). A malignant tumor that originates in the nuclear layer of the retina. "Here we focused on the role of the ligands of ACVR1C receptor, which include Nodal, Activin and growth/differentiation factor 3 (GDF3), to determine the origin of this pro-metastatic signaling in retinoblastoma cells." (PMID 31451106, 2019). "We specifically focused on Nodal as we previously observed upregulated expression of this ligand at the mRNA and protein levels in multiple retinoblastoma lines, as compared to the other two ligands, Activin and GDF3, which were expressed at lower levels and only in a few of the cell lines tested." (PMID 31451106, 2019).
acute lung injury (1 paper, 2024). A condition of lung damage that is characterized by bilateral pulmonary infiltrates (pulmonary edema) rich in neutrophils, and in the absence of clinical heart failure. "However, the precise mechanism of GDF3 in acute lung injury (ALI) remains incompletely understood." (PMID 38543054, 2024).
alcoholic hepatitis (1 paper, 2022). Acute hepatitis resulting from ingestion of alcohol. "Interestingly, hepatic GDF3 expression was significantly increased in patients with NASH, but it was unchanged in patients with alcoholic hepatitis, autoimmune hepatitis, drug-induced liver injury, and hepatitis B virus infection." (PMID 39872077, 2022).
breast tumor (1 paper, 2023). "In support of this evidence, recently it is revealed that GDF3 expression was limited to 7.7% (9/117) of primary breast tumor samples and was correlated with the absence of axillary lymph node metastasis, suggesting a protective effect of GDF3." (PMID 37205315, 2023).
hepatoma (1 paper, 2010). "We then examined the expression of GDF3 in mouse hepatoma G1 and G5 cell lines." (PMID 20950440, 2010). "Overexpression of GDF3 did not affect the growth of mouse hepatoma high or low metastatic sublines G5 or G1, both of which do not express GDF3." (PMID 20950440, 2010). "In this regard, ectopic expression of GDF3 did not promote tumorigenesis of mouse hepatoma G1 and G5 cells." (PMID 20950440, 2010).
hydatidosis (1 paper, 2020). "In addition, miR-184 may regulate the function of pancreatic beta-cells through glucose metabolism, alter insulin secretion, and thus down-regulate the GDF3 gene, leading to the final infection of hydatidosis in canine." (PMID 32596042, 2020).
liver diseases (1 paper, 2022). "To understand the clinical relevance of our animal model-based observations, we analyzed GDF3 expression in the livers of patients with various liver diseases using GEO datasets." (PMID 39872077, 2022).
lymph node metastasis (1 paper, 2023). "Although there was not any significant association between GDF3 expression and other clinicopathological aspects such as tumor stage, grade of differentiation, and lymph node metastasis, 4 of 7 GDF3 overexpressed tumors (57.1%) were in advanced stages (III/IV), MD, showing lymph node metastasis." (PMID 37205315, 2023).
macrosomia (1 paper, 2022). "Moreover, we constructed ROC curves and graphical nomogram to evaluate the risk prediction performance of the expression of the validated genes for GDM-related macrosomia and found that GDF3 expression and AC006064.4 expression in peripheral blood exosomes had good prediction performance." (PMID 35547007, 2022).
steatosis (1 paper, 2022). Increased lipid within the cytoplasm of cells. "Plasma GDF3 levels were strongly associated with the NAS score and individual histologic features, including steatosis, ballooning, and lobular inflammation." (PMID 39872077, 2022).
testicular cancer (1 paper, 2015). A primary or metastatic malignant neoplasm that affects the testis. "GDF3 potentiates NODAL activity, but has also been related to the development of testicular cancer formation." (PMID 26630562, 2015).
ZIKV infection (1 paper, 2022). "The present study aimed to evaluate the serum levels of GDF-3 and inflammasome-related markers in pregnant women during acute ZIKV infection." (PMID 35632746, 2022). "The results showed that acute ZIKV infection induces more intensive GDF3, NLRP3, IL-1β, and IL-18 expression in the context of pregnancy." (PMID 35632746, 2022). "In conclusion, this study demonstrated that acute ZIKV infection during pregnancy triggers overexpression of the growth factor GDF3 and the inflammasome-related factors NLRP3, IL-1β, and IL-18." (PMID 35632746, 2022). "Thus, this study evaluated the serum levels profile of GDF3 and inflammasome-related markers in pregnant women during acute ZIKV infection." (PMID 35632746, 2022). "The findings indicated that acute ZIKV infection during pregnancy induces the overexpression of GDF-3 and inflammasome-related markers, which may contribute to congenital disorders and harmful pregnancy outcomes." (PMID 35632746, 2022). "Serum samples from pregnant (n = 18) and non-pregnant (n = 22) women with acute ZIKV infection were assessed for NLRP3, IL-1β, IL-18, and GDF3 markers through an enzyme-linked immunosorbent assay." (PMID 35632746, 2022).
tumor (10 papers, 2010 to 2025). "On the other hand, downregulation of the TGF-β family growth differentiation factor 3 and the apelin receptor genes Gdf3 and Aplnr is associated with promoting tumor growth, angiogenesis, and metastasis 60,61." (PMID 41377951, 2025). "GDF15 (P = 1.62E‐12), GDF11 (P = 1.38E‐2), GDF9 (P = 7.2811E‐3), and GDF3 (P = 4.95E‐6) were significantly up-regulated in primary tumor tissue (n = 415) compared with that in normal tissue (n = 34)." (PMID 40153751, 2025). "Expression of GDF3 in tumor tissues from 40 ESCC patients was compared to the related margin normal tissues by relatively comparative real-time polymerase chain reaction (PCR)." (PMID 37205315, 2023). "Excluding for 1, all of the patients with GDF3 overexpression had the invasion of tumor cells to the adventitia (6 of 7), which emphasizes the probable role of this factor in the invasiveness of the disease." (PMID 37205315, 2023). "The mRNA expression level of GDF3 in the fresh frozen neoplastic tissue was compared to the distant resected tumor-free esophageal epithelium by quantitative real-time RT-PCR." (PMID 37205315, 2023). "Using the NCCIT cell line, it was revealed that GDF3 induced expression of the genes pertinent to cell differentiation, which can act as strong tumor suppressors, such as Hox-family genes." (PMID 37205315, 2023). "The expression of GDF3 mRNA was significantly correlated with the depth of tumor invasion (P < 0.05)." (PMID 37205315, 2023). "GDF3 was significantly overexpressed in 17.5% of tumors and a significant correlation between GDF3 expression and the depth of tumor invasion was observed (P = 0.032)." (PMID 37205315, 2023). "The upregulated gene set also included known genes related to pluripotency and growth, such as KLF5, FGF4 and GDF3, and 8 downregulated genes were known tumor suppressors." (PMID 28837588, 2017). "The results infer that the GDF3 message is translated into functional protein in these tumor cells and forced expression of GDF3 are still minimally expressed 10 days after transfection in these cells." (PMID 20950440, 2010). "We found that endogenous growth-differentiation factor 3 (GDF3) expression was induced in implant B16 tumor during tumor progression in syngenic C57BL/6 mice." (PMID 20950440, 2010). "FACS analysis showed that tumor cells with GDF3-expressing vector contained more CD24 and CD44 double-positive cells than those transfected with the empty vector." (PMID 20950440, 2010). "Having considered the importance of CSC markers identification and their exploitation in targeted cancer therapy, GDF3 may be introduced as a promising therapeutic target to inhibit the invasion of tumor cells in ESCC." (PMID 37205315, 2023). "Moreover, 85.7% of GDF3 overexpressed samples were invaded to the adventitia (T3, 4), emphasizing the remarkable role of GDF3 overexpression in tumor progression and invasion of ESCC." (PMID 37205315, 2023). "Overexpression of GDF3 mRNA was observed in 7 of 40 tumor samples (17.5%)." (PMID 37205315, 2023). "With regard to GDF3, in our cohort we found that its expression was limited to 7.7% of primary BC tumor samples and was associated with the absence of axillary lymph node metastasis (p=0.029), thus suggesting a protective effect of GDF3." (PMID 25127259, 2014). "Consistently, Li and colleagues showed that GDF3 proteins could inhibit the proliferation of MCF-7 and T47D cells and that the knockdown of GDF3 enabled colony formation and tumor progression in human BCs." (PMID 25127259, 2014). "Other highly interesting GDF3 targets were also reported to act as potent tumor suppressors." (PMID 23950971, 2013). "We examined the mechanism by which GDF3 accelerates tumor growth." (PMID 20950440, 2010). "Interestingly, the overexpression of GDF3 increased the tumor diameters in both B16-F1 and B16-F10 cells." (PMID 20950440, 2010). "By what mechanism TGF-β-like GDF3 induces up-regulation of CD24 on tumor cells, however, remains unknown." (PMID 20950440, 2010).
tumor (continued). "In this study, the expression level of the GDF3 in ESCC patients was evaluated and its overexpression was found in 17.5% of tumor tissues at the mRNA level in significant correlation with the depth of tumor cell invasion." (PMID 37205315, 2023). "Either way, this is the first report on the embryonic antigen GDF3 which is an inducer of CD24 and joins tumor cell proliferation." (PMID 20950440, 2010). "GDF3 is a member of TGF-β super family which is expressed in ES cells and in several human tumor cells." (PMID 20950440, 2010). "Stem cell markers, such as NANOG, OCT3/4 and GDF3, contribute to the maintenance of tumor cell pluripotency, and genes involved in proliferation and cell cycle control, including KI67 and CDK4, promote tumor growth." (PMID 37174085, 2023). "This GDF3-BMP link might be considered in designing anti-cancer treatment, since active BMP signaling in tumor has been reported to be beneficial for the disease outcome." (PMID 23950971, 2013). "We observed that GDF3 robustly induces a panel of genes related to differentiation, including several potent tumor suppressors, without impacting the proliferative capacity." (PMID 23950971, 2013). "Ecat1, Dppa5, and GDF3 genes are expressed in ES cells, but their expression in tumor has not yet been reported." (PMID 20950440, 2010). "Furthermore, 86.3% of patients (19 of 22) with no metastasis of tumor cells to the lymph nodes did not have GDF3 overexpression." (PMID 37205315, 2023).